KRAS (KRas proto-oncogene, GTPase)
Diseases named in the same sentence as KRAS in open-access papers (continued):
Sharing a sentence is not in itself a finding about the gene and the disease.
non-small cell lung carcinoma (continued). "Using non-small cell lung cancer (NSCLC) as an example of a high-degree disease node, potential links between NSCLC and genes such as KRAS, LINC00963, and MIR17HG are discovered." (PMID 39797570, 2025). "The RAS family of oncoproteins (KRAS, HRAS, and NRAS) drive aggressive cancers like pancreatic ductal adenocarcinoma (PDAC) and non-small cell lung cancer (NSCLC), yet targeting mutant RAS has historically been challenging due to its “undruggable” structure." (PMID 41471277, 2025). "Key gaps and needs in targeting KRAS/BRAF/MET and other genomic alterations in non-small-cell lung cancer." (PMID 39237103, 2025). "In the context of target therapies, G12D and G12S KRAS non-small cell lung cancer (NSCLC) patients treated with EGFR TKIs showed promising response rates compared with G12C and G12V KRAS-bearing patients." (PMID 38261067, 2024). "These regulatory networks encompassing circ_0048856-miR-1287-5p, circ-MEMO1-miR-101-3p-KRAS, and circ_00007355-miR-345-5p-ADAM19 play a role of detection of non-small cell lung cancer." (PMID 39021878, 2024). "Paradigm defining examples are targeted therapies directed against non-small cell lung cancer (NSCLC) subtypes with oncogenic alterations in EGFR, ALK and KRAS." (PMID 38702301, 2024). "Mutant KRAS promotes the proliferation, metastasis, and aggressiveness of various cancers including pancreatic ductal adenocarcinoma (PDAC), non-small cell lung cancer (NSCLC), and colorectal adenocarcinoma (CRC) respectively." (PMID 39453574, 2024). "Christian F Ruiz's team found that mutant KRAS promotes the de novo lipid synthesis and the SREBP1-mediated mitochondrial gene expression in non-small cell lung cancer, and mutant KRAS tumor cells are susceptive to FASN inhibitors." (PMID 38560498, 2024). "CD73 expression amplifies in lung tumors, especially non-small cell lung cancer (NSCLC), often aligned with key oncogenic drivers like mutant EGFR and KRAS." (PMID 38067409, 2023). "KRAS is a gatekeeper gene in colorectal tumorigenesis as well as pancreatic ductal adenocarcinoma (PDAC) and non-small-cell lung cancer (NSCLC) and is thus an attractive target." (PMID 36831298, 2023). "In non-small cell lung cancer (NSCLC), colorectal cancer (CRC), and pancreatic ductal adenocarcinoma (PDAC), FSP1 is expressed at higher levels in KRAS mutant tumor cells compared to normal cells." (PMID 37834062, 2023). "The recent development of KRAS-G12C inhibitors and their consequent FDA approval for non-small cell lung cancer shows the benefits and limitations of directly inhibiting RAS drivers, and highlights the importance of targeting other members of the RAS family." (PMID 37503077, 2023). "Sotorasib and Adagrasib, both FDA-approved for the treatment of non-small cell lung cancer (NSCLC), have been pivotal in paving the way for KRAS G12C inhibitors in the clinical setting." (PMID 37190303, 2023). "Recently, two small molecules KRAS inhibitors, sotorasib and adagrasib were granted FDA approval in 2021 and in 2022 for the treatment of KRAS G12C mutant non-small cell lung cancer." (PMID 38239196, 2023). "Further increased YAP nuclear localization has also been reported to be associated with chemotherapy resistance and relapse in EGFR-mutant, KRAS-mutant and B-RRAF mutant, ALK-rearranged non-small-cell lung cancer and RAS-driven neuroblastoma." (PMID 36523977, 2022). "The A549 cell line, a KRAS mutant and an EGFR wild type epithelial carcinoma obtained from a 58-year-old male patient, is one of the most commonly used cell lines to model non-small cell lung cancer (NSCLC)." (PMID 36077349, 2022).
non-small cell lung carcinoma (continued). "In non-small cell lung cancers, KRAS G12C/V activated the Ral pathway but reduced AKT phosphorylation, whereas KRAS G12D activated phosphatidylinositol 3-kinase (PI3K) and mitogen-activated protein/extracellular signal-regulated kinase kinase (MEK) signaling." (PMID 34233735, 2021). "In this multicentre study of 1117 patients with stage I–IV non-squamous non-small cell lung carcinoma (NSCLC), we investigated associations between KRAS and clinical characteristics and survival." (PMID 34503114, 2021). "Treatment planning for non-small cell lung cancer requires testing for EGFR, ALK, ROS1, BRAF, MET, RET and KRAS gene alterations." (PMID 34681592, 2021). "In mutant KRas-driven non-small-cell lung cancer (NSCLC) model system, NSC290956 effectively suppresses the KRas-GTP state and gives pharmacological KRas inhibition with concomitant blockages of both the MAPK-ERK and AKT-mTOR pathways." (PMID 35069209, 2021). "The functionalization of surface carboxylic acids with folate allowed targeting and, consequently, enhanced uptake by the non-small cell lung cancer (NSCLC) cell line A549, an epithelial carcinoma that is a KRAS mutant." (PMID 33912379, 2021). "The present study was designed to determine the potential significance and the clinical relevance of two RAS gene family isoforms (KRAS and HRAS) and their mRNA expression levels in the group of non-small-cell lung cancer patients." (PMID 33549031, 2021). "Moreover, TAK1 plays a key role in tumor-associated macrophages, promoting non-small cell lung carcinoma (NSCLC) growth and apoptosis in KRAS-dependent colon cancer." (PMID 33375627, 2020). "ctDNA analysis of epidermal growth factor receptor (EGFR) in non-small cell lung cancer (NSCLC) and v-Ki-ras2 kirsten rat sarcoma viral oncogene homolog (KRAS) in colorectal cancer (CRC) is well established." (PMID 32010431, 2020). "On the other hand, in non-small cell lung cancer (NSCLC), a staggering ≈60% of the tumors had alterations in chief “driver oncogenes” including EGFR, BRAF, and KRAS combined." (PMID 31426419, 2019). "Activation of KRAS signaling along with homozygous deletion of LKB1 (also known as STK11 or serine/threonine kinase 11) promoted cancer progression and metastasis in non-small cell lung cancer models." (PMID 31681559, 2019). "For example, the three genes KRAS, EGFR, and ERBB2(HER2), which are found in the non-small cell lung cancer (NSCLC) signaling network, are key biomarkers." (PMID 29912931, 2018). "In recent years, series of driver genes, such as EGFR, KRAS/NRAS, BRAF, PIK3CA, ALK and ROS1 and so on, have been found in non-small cell lung cancer (NSCLC) one after another with the development of molecular detecting technology." (PMID 29526181, 2018). "Tracing of glucose and glutamine fate in tumors derived from human non-small cell lung cancer (NSCLC) and mouse KRAS-driven NSCLC found that these tumors rely more on glucose than on glutamine for TCA cycle anaplerosis." (PMID 28826492, 2017). "Epidermal growth factor receptor (EGFR), Kirsten rat sarcoma viral oncogene homolog (KRAS) and anaplastic lymphoma kinase (ALK) are all significant biomarkers for the management of non-small-cell lung cancer (NSCLC)." (PMID 28881771, 2017). "Epidermal growth factor receptor (EGFR), and anaplastic lymphoma kinase (ALK), are important oncogenic drivers in non-small-cell lung cancer (NSCLC), and other oncogenic drivers in NSCLC, such as ROS1 and KRAS, have also been found." (PMID 27533086, 2016). "EGFR, KRAS, and ALK alterations are major genetic changes found in non-small cell lung cancers (NSCLCs)." (PMID 26992209, 2016). "In a recent study, transcriptome-wide sequencing of non-small cell lung cancer (NSCLC) type with wild-type and mutant KRAS revealed 73,717 SNVs that consisted of both germ-line and somatic variants." (PMID 24416147, 2014).
non-small cell lung carcinoma (continued). "Our objective was to sequence KRAS and compare expression of NQO1 as well as a panel of five clinically relevant proteins in 108 non-small cell lung carcinoma (NSCLC), the most common form of LC, patients with and without KRAS mutations." (PMID 25222473, 2014). "It is mandatory to confirm the absence of mutations in the KRAS gene before treating metastatic colorectal cancers with epidermal growth factor receptor inhibitors, and similar regulations are being considered for non-small cell lung carcinomas (NSCLC) and other tumor types." (PMID 22995035, 2012). "The molecular pathogenesis of lung NENs is complex and varies across the different subtypes, typically lacking common oncogenic driver mutations found in non-small cell lung cancer (NSCLC), such as KRAS and EGFR in lung adenocarcinomas." (PMID 40586102, 2025). "For instance, combining selumetinib, a MEK inhibitor, with docetaxel did not enhance overall survival in previously treated KRAS mutant non-small-cell lung cancer (NSCLC) patients." (PMID 40611261, 2025). "These trials do not include pan-RAS or RAS mutant inhibitors such as the KRAS G12C inhibitors sotorasib or adagrasib which recently achieved FDA approval for non-small cell lung cancer." (PMID 39221276, 2024). "In these clinical studies, CB-839 has been administered with nivolumab as a treatment for melanoma, renal cell carcinoma (RCC), and non-small cell lung cancer (NSCLC); everolimus for RCC; palbociclib for KRAS-derived PDAC, NSCLC and CRC; and cabozantinib for advanced RCC." (PMID 38473414, 2024). "The main druggable genetic alterations in non-small cell lung cancer involved EGFR (epidermal growth factor receptor), KRAS (Kirsten rat sarcoma viral oncogene homolog), ALK (anaplastic lymphoma kinase), BRAF (V-raf murine sarcoma oncogene homolog B1), and ROS1 (c-ros oncogene 1) genes." (PMID 39199653, 2024). "In non-small cell lung cancer (NSCLC), sotorasib gained accelerated USFDA approval on the basis of a phase II trial demonstrating an impressive ORR of 37.1% and disease control rate (DCR) of 80.6% in pretreated patients with KRAS G12C mutant NSCLC." (PMID 35681599, 2022). "Nevertheless, a few studies investigated into the impact of mutational status for patients with non-small cell lung carcinoma (NSCLC) having irradiation of existing brain metastases, and they mostly reported the negative impact of KRAS mutation on local, intracranial and overall relapse." (PMID 36163026, 2022). "Similarly, mutant KRAS is present in 30–40% of colorectal cancers (CRC) and almost 25% of patients with Non-Small Cell Lung Cancer (NSCLC), where it correlates with poor prognosis and high risk of recurrence." (PMID 34485382, 2021). "Atorvastatin reverses gefitinib resistance in KRAS-mutant non-small cell lung carcinoma, irrespective of PIK3CA and PTEN status." (PMID 34065757, 2021). "A clinical trial of restapimycin (IPI-504) and everolimus (an mTOR inhibitor) has been conducted in patients with KRAS-mutant non-small cell lung cancer, however study results are not yet public (NCT01427946)." (PMID 34502310, 2021). "Primary resistance to CTX is mainly due to aberrations in the KRAS, NRAS, and EGFR genes, which are often found in other cancer backgrounds, including colorectal cancer (CRC) and non-small cell lung cancer (NSCLC) but are uncommon in HNSCC tumours in CTX-naïve patients." (PMID 35008337, 2021). "The intense desmoplastic histologic feature is not a cardinal feature of other KRAS-mutant cancer types such as non-small cell lung cancer (NSCLC), colorectal cancer, (CRC) or multiple myeloma." (PMID 34771644, 2021). "For instance, in non-small cell lung cancer patients with no available tumor biopsy, blood is the only source for detecting genetic alterations, including EGFR, KRAS, BRAF, PIK3CA mutations, and ALK rearrangements." (PMID 34359285, 2021).
non-small cell lung carcinoma (continued). "miR-21 also enhances oncogenic KRAS activity and tumorigenesis by targeting negative KRAS pathway regulators in non-small cell lung cancer." (PMID 32545208, 2020). "In non-small cell lung cancer (NSCLC), the most frequent oncogenic mutation in western countries is KRAS, for which, however, there remains no clinically approved targeted therapies." (PMID 31612108, 2019). "PD-0325901 failed in its phase II clinical trials for the treatment of KRAS mutant non-small cell lung cancer by not meeting its primary efficacy end-point (ClinicalTrials.gov number, NCT00174369)." (PMID 28954413, 2017). "Although the development and clinical trial of selumetinib has focused on KRAS-mutant non-small-cell lung cancer or BRAF-mutant melanoma, it is not clear that MEK inhibitors are specific for KRAS-mutant cancers." (PMID 29296181, 2017). "The purpose of this study was to test genetic biomarkers used in clinical practice (EGFR, ALK) and candidate biomarkers identified by the French National Cancer Institute (KRAS, BRAF, PIK3CA, HER2) in patients with metastatic non-small-cell lung cancer for whom two tumor samples were available." (PMID 26968843, 2016). "None of the patients underwent tests for EGFR mutation, KRAS mutation, or ALK gene rearrangement, although 9 of the patients had non-small cell lung cancer of nonsquamous histology." (PMID 27445531, 2016). "Recent studies have shown that KRAS mutations are negative predictors of benefit from both adjuvant chemotherapy and anti-EGFR directed therapies for non-small cell lung carcinoma (NSCLC)." (PMID 29147262, 2011). "However, a later randomized, multicenter, placebo-controlled, phase II study of selumetinib combined with docetaxel for KRAS-mutant advanced non-small-cell lung cancer did not reveal a statistically significant improvement." (PMID 40597785, 2025). "Non-small cell lung cancer (NSCLC) has one of the highest CD73 expression signatures among all cancer types and the presence of common oncogenic drivers of NSCLC, such as mutant epidermal growth factor receptor (EGFR) and KRAS, correlate with increased CD73 expression." (PMID 37033953, 2023). "Besides in PDAC some progress has already been achieved with these molecules in several treatment-resistant forms of cancer, including KRAS-mutant and TKI-resistant non-small cell lung cancer, castration-resistant prostate cancer, endometrial cancer, leukemia and neuroblastoma." (PMID 37170215, 2023). "In recent years, the use of anti-EGFR mAbs has played an increasing role in the treatment of several solid tumour types including non-small-cell lung carcinoma (NSCLC), colorectal cancer (CRC), and head and neck squamous cell carcinoma (HNSCC) in which KRAS mutation is not detected." (PMID 35814459, 2022). "In clinical studies, patients with Stage I non-small cell lung cancer (NSCLC) or liver metastasis treated with ablative radiation (i.e. stereotactic body radiation therapy, SBRT) whose tumors were KRAS mutant had worse local control compared to patients with KRAS wild-type tumors." (PMID 34537078, 2021). "RET kinase domain fusion with kinesin family member 5B was identified in about 1–2% of patients with non-small-cell lung cancer (NSCLC), who were negative for mutations or rearrangements in other common oncogenic drivers such as EGFR, HER, ERBB2, BRAF, KRAS, ALK, etc.." (PMID 32993133, 2020). "Predictive biomarkers of tumor response to EGFR inhibitors have been well established in non-small cell lung cancer (NSCLC) and colorectal cancer (CRC) but these mechanisms (including EGFR and KRAS mutations) are extremely rare and are not clinically relevant to HNSCC." (PMID 31346466, 2019). "Next-generation forms of KRAS G12C targeting agents, including ARS-1620, demonstrated improved potency compared to earlier generation agents and block oncogenic RAS signaling and tumor growth in vivo in a target-specific manner in non-small cell lung cancer models." (PMID 31681559, 2019).
non-small cell lung carcinoma (continued). "However, MEK inhibitors have failed to induce clinical responses in KRAS mutant advanced non-small cell lung cancer." (PMID 27014419, 2016). "Clinical studies in other tumor entities, such as metastatic colorectal and non-small cell lung cancer, have shown that the use of anti-EGFR antibodies or tyrosine kinase inhibitors improves progression free and overall survival, but only for patients lacking a KRAS mutation." (PMID 32796566, 2020). "In conclusion, the genetic mutations associated with PACC are different from those implicated in non-small cell lung cancer, and EGFR, KRAS, BRAF, ALK, PIK3CA, PDGFRA, and DDR2 may not be driver genes in PACC; we must identify other genes for targeted therapy against PACC." (PMID 26373952, 2015). "We sequenced KRAS and investigated expression of NQO1 and five clinically relevant proteins (DNMT1, DNMT3a, ERK1/2, c-MET, and survivin) in 108 patients with non-small cell lung carcinoma (NSCLC)." (PMID 25222473, 2014). "Aberrant signaling transduction induced by mutant KRAS proteins occurs in 20∼30% of non-small cell lung cancer (NSCLC), however, a direct and effective pharmacological inhibitor targeting KRAS has not yet reached the clinic to date." (PMID 28443025, 2017). "For patients with advanced and or unresectable non-small cell lung cancer (NSCLC) who do not fit an approved molecular targeted therapy (e.g., KRAS wild-type), treatment options include regimens of radiotherapy and platinum-based chemotherapy, with or without immune therapy." (PMID 39338298, 2024).